SMAD3 (SMAD family member 3)
Diseases named in the same sentence as SMAD3 in open-access papers (continued):
Sharing a sentence is not in itself a finding about the gene and the disease.
colon carcinoma (continued). "Smad3 knockout mice develop colon tumours by 6 months of age." (PMID 21063400, 2011). "Therefore, downregulation of Smad4, or treatment with inhibitors to inhibit TGFβ signaling or Smad2 and/or Smad3 phosphorylation, combined with Dox may be a potential novel strategy with which to treat colon cancer." (PMID 25684678, 2015). "Although Rab25-deficient mice do not develop spontaneous colon tumours, breeding of ApcMin mice onto the Rab25-deficient background induces a marked increase in tumours, and crossing of Smad3+/− mice onto the Rab25 knockout background yields large invasive tumours." (PMID 21063400, 2011). "It has been shown that the expression of PHGDH is regulated by many transcription factors, such as HOXA10, SMAD3 and ATF3, in endometrial endothelial cells, pulmonary epithelial cells and colon cancer cells." (PMID 39962071, 2025). "To exclude Smad3/Smad4-mediated transcriptional induction of ID1, we used Smad4-null SW620 and HT29 colon cancer cells." (PMID 33990575, 2021). "Taken together, our studies demonstrate that TGFβ/Smad3 inhibits cell proliferation and induces apoptosis through down-regulation of IRS-1 expression/activation in colon cancer cells." (PMID 28414818, 2017). "Taken together, our study suggests a novel model of crosstalk between TGFβ/Smad3 signaling and IRS-1 in colon cancer cells." (PMID 28414818, 2017). "Previous studies about transcription regulation signaling pathway suggested that FOXM1 transcriptionally regulated of downstream genes such as TGF-β/SMAD3/4 to promote cancer metastasis and induced PRX3 to regulates stemness and survival of colon cancer cells." (PMID 27716361, 2016). "From the common edible plants 11 were found to have compounds targeting 3 proteins (MARK1, SMAD3, GSK3B) of the KEGG colon cancer pathway and 28 targeting the remaining 9, which are first-degree neighbors of the proteins in the KEGG colon cancer pathway." (PMID 24886433, 2014). "In contrast, two hub genes of colon cancer, SMAD2 and SMAD3, are from the TGFβ/SMAD signaling pathway whose role is more established for the development of colon cancer compared to the other two cancer types." (PMID 22691569, 2012). "Therefore, we investigated the role of SPTBN1-cleaved fragments in ammonia-mediated alterations in TGF-β–SMAD3 signaling, utilizing siRNA targeting SPTBN1 (siSPTBN1) in SW480 and Caco-2 human colon cancer cells and treated cells with ammonia." (PMID 40311681, 2025). "This interaction stimulates SMAD3 phosphorylation and activates the SMAD2-3-4 signaling pathway, resulting in the inhibition of cyclin D1/CDK4 expression and leading to G1 cell cycle arrest in colon cancer cells." (PMID 38338430, 2024). "The fact that SMAD3 undergoes APA, may be of significance in the context of colon cancer progression." (PMID 31147722, 2019). "TGF-β-dependent signaling activates PTHLH expression by increasing transcription from the P3 promoter through a synergistic interaction of the transcription factors Smad3 and Ets1, and p38 MAPK-dependent signaling controls PTHLH expression in metastatic colon cancer cells." (PMID 31487323, 2019). "Since Smad3 is an important effector in TGFβ signaling, we next determined whether downregulation of Smad3 would affect IRS-1 expression and activation in colon cancer cells." (PMID 28414818, 2017). "The observation of increased activation of SMAD3 and the strong modulation of TGF-β target genes in consequence of 5FU treatment in chemoresistant colon carcinoma cells, led us to hypothesize a possible role of the TGF-β molecule in the cell response to 5FU." (PMID 26956045, 2016). "In our colony, Smad3−/− mice (9 months and older) given untreated water and maintained Helicobacter-free do not develop colitis or colon cancer." (PMID 24244446, 2013).
colon carcinoma (continued). "Although our results indicated that Smad3−/− mice were more susceptible to DSS colitis than Smad3+/− mice, the majority of DSS-treated Smad3−/− mice in this study did not survive long enough to develop dysplasia or colon tumors." (PMID 24244446, 2013). "Interestingly, the potent inflammation-inducing agent dextran sodium sulfate (DSS) in the absence of Helicobacter does not induce colon cancer in the Tgfb1−/−Rag2−/− model and induces only a few late-onset tumors in the Smad3−/− model." (PMID 28951889, 2017). "The increase in nuclear localization of SMAD3 in our in vivo and in vitro models of chemoresistance together with the modulation of TGF-β target genes only in chemoresistant, 5FU-treated, colon carcinoma cells led us to hypothesize a possible role of the TGF-β molecule in the response to 5FU." (PMID 26956045, 2016).
Obesity (50 papers, 2012 to 2025). Accumulation of substantial excess body fat. "Its upregulation has been linked to lipid-induced stress via the TGFβ-SMAD3 signaling pathway, and its dysregulation has been observed in insulin-resistant conditions such as polycystic ovary syndrome and obesity." (PMID 41385529, 2025). "Deficiency in Smad3 protects against insulin resistance and obesity induced by a high-fat diet, while in gut it regulates TGF-β auto induction in Clostridium butyricum-activated dendritic cells." (PMID 36788222, 2023). "TGFB-Beta/Smad3 signaling has been implicated in various obesity–inflammation pathways, including the endocrine organ secretion of adipocytokines (e.g., leptin and resistin)." (PMID 36142918, 2022). "In line with this, TGFβ/SMAD3 signalling regulates insulin transcription in pancreatic islet β-cells, whereas SMAD3 deficiency in mice protects against insulin resistance and type 2 diabetes during high-fat-diet-induced obesity." (PMID 32722512, 2020). "Using hyperinsulinemic-euglycemic clamp experiments, this group reported that Smad3 loss protects experimental mice from diet-induced obesity and insulin resistance." (PMID 25364764, 2014). "The TGF-β/Smad3 signaling pathway is also implicated in obesity, inflammation, and diabetes." (PMID 36142918, 2022). "The pleiotropic effects of TGF-β/Smad3 signaling on cell metabolism and energy homeostasis plays an important part in the progression of obesity-linked diabetes; these include adipocyte differentiation, adipose browning, inflammation and regulation of insulin signaling amongst others." (PMID 33897620, 2021). "Indeed, Smad3-deficient mice are resistant to HFD-induced obesity and diabetes." (PMID 34948212, 2021). "We observed altered microbial populations in an obesity-induced mouse model of cancer, where ammonia promotes caspase-3-mediated cleavage of the SMAD3 adaptor βII-spectrin (SPTBN1)." (PMID 40311681, 2025). "Smad3 (SMAD Family Member 3) is a transcription factor involved in many diseases, including obesity and metabolic disorder." (PMID 37600712, 2023). "The miR-10a-3p mimic significantly reduced levels of various inflammatory cytokines and blocked excess lipid accumulation in adipocytes through the TGF-β1/Smad3 pathway during obesity." (PMID 37334370, 2023). "The TGF-β/Smad3 mechanistically links many comorbidities with obesity through its profibrotic, remodeling, and proinflammatory functions." (PMID 36142918, 2022). "In one experimental study, a suppression of the TGF-β/Smad3 pathway in WAT was shown to reduce obesity and regulate energy homeostasis/glucose tolerance in vitro." (PMID 34835958, 2021). "The same group assessed the effect of blocking TGF-β/Smad3 signaling in two well-characterized mouse models of obesity and type 2 diabetes." (PMID 33897620, 2021). "Together, CCN5 knockout would result in increased adipocyte differentiation, activated TGF-β/Smad3 pathway, and the expression of adipogenic genes, which all contribute to mild obesity." (PMID 34948212, 2021). "Recent studies have clearly established an essential role of TGF-β/Smad3 signaling in the pathogenesis of obesity and type 2 diabetes." (PMID 33897620, 2021). "Then we validated 7 obesity or lipid metabolism related genes (Hif1a, Spon1, H19, Adrb2, Vldlr, Zfp36, Smad3), and found that compared to CTL group, Vldlr was hypermethylated and low expressed, and Hif1α was demethylated and high expressed in the VDD group." (PMID 29321608, 2018). "Previous in vivo animal studies also suggested the role for Smad3 in mediating high-fat diet induced obesity and insulin resistance." (PMID 30409165, 2018). "Specifically, the methylation levels of FGFRL1, NCAPH2, PNKD and SMAD3 exhibited excellent and statistically significant efficiencies in the discrimination of obesity from non-obesity status (AUC > 0.80; p < 0.05) and a great correlation between both tissues." (PMID 28211912, 2017).
Obesity (continued). "Most recently, a comprehensive study highlighted the critical involvement of TGF-β/Smad3 signaling during the process of obesity and demonstrated the beneficial effects of systemic blockade of this signaling from obesity, diabetes, and hepatic steatosis." (PMID 25364764, 2014). "In line with this, diet-induced obesity elevates the level of activated phospho-Smad3 in mouse adipose tissue." (PMID 25161195, 2014). "As expected, the protein expressions of TGF-β and phosphorylated Smad3, two indices of fibrosis, were significantly higher in obesity than in control and obese reduction, and significantly higher in obese reduction than in control (all p<0.005)." (PMID 22784636, 2012). "Together, our study highlighted oxymatrine could suppress high-fructose and high-fat diet-induced obesity by inhibiting the suppressor of mothers against decapentaplegic 3 (Smad3) binding on obesity-related enhancers." (PMID 37600712, 2023). "Overall, CD52 may functioned as an important potential target for obesity with T2DM via TGF-β/Smad3 axis." (PMID 33705353, 2021). "Smad3−/− mice displayed protection against diet-induced obesity and related metabolic syndromes." (PMID 33897620, 2021). "Considering the critical potential role of Smad3 signaling in obesity, further studies are required to explore whether RA could positively affect adipose tissue function under obese conditions." (PMID 28659738, 2017). "Smad3 deleted mice are protected from insulin resistance and high fat diet induced obesity." (PMID 24986741, 2014). "In addition, variants near the NFKB1 gene have been associated to T2D based on the DIAGRAM dataset (best nearby SNP p-value = 1.6×10−5), while SMAD3 has been recently found to protect against diet-induced obesity as well as coronary artery disease." (PMID 23236286, 2012). "In addition, a previous study reported that inhibition of SMAD3 ameliorates obesity in rodents." (PMID 37600712, 2023). "Moreover, and in contrast to its anti-inflammatory effects in other tissues, TGF-β/Smad3 signaling causes adipocyte hypertrophy, hyperplasia, and increased production of inflammatory cytokines, which together with TGF-β contribute to obesity-associated adipose tissue fibrosis." (PMID 35628290, 2022). "Moreover, the expression of FGFRL1, PNKD, PODXL, PTPRCAP, SMAD3 and WDR45L based on previously reported data correlated inversely with the methylation levels in the subcutaneous adipose tissue suggesting a potential epigenetic regulation associated to obesity." (PMID 28211912, 2017). "TGF-β has been shown to activate the downstream gene Smad3, which inhibits the expression of PPARγ coactivator-1α (PGC-1α) gene, potentially leading to mild obesity in individuals with reduced CCN5 expression." (PMID 37794318, 2023). "The genetic depletion of Smad3 and systemic treatment with anti-TGF-β antibody has been shown to protect mice from diet-induced obesity, insulin resistance, and hepatic steatosis." (PMID 31658594, 2019). "We also identified six DMRs which mapped to obesity and related metabolic traits in the GWAS catalogue (PROX1, PHACTR1, SLC22A8, SMAD3, LCAT, DNM2)." (PMID 25651499, 2015). "Furthermore, metformin, the first‐line drug for treating obesity‐related T2D, activates AMPK and suppresses TGF‐β1/Smad3 signaling, suppressing abnormal ECM remodeling in WAT and ameliorating IR in individuals with obesity." (PMID 38812572, 2024). "In addition, the TGF-β-Smad3 pathway has been shown to be important for the differentiation of brown adipocytes, the balance of WAT/BAT transition, and the modulation of obesity in several mouse studies." (PMID 31658594, 2019). "TGF-β1/Smad3 activation contributes to persistent and aberrant ECM remodeling of VAT in obesity, and modulation of TGF-β1 activity might be an effective treatment strategy for obesity and related diabetes." (PMID 31332184, 2019).
Obesity (continued). "Relevantly, the areas under the ROC curves (AUCs) for FGFRL1, NCAPH2, PNKD, and SMAD3 evidenced excellent and statistically significant efficiencies in discriminating obesity from non-obesity in both the subcutaneous adipose tissue and leukocytes." (PMID 28211912, 2017). "However, how miR-10a-3p mediates TGF-β1/Smad3 expression, adipogenesis, and AT inflammation via crosstalk between immune cells and adipocytes is not well established in the context of obesity." (PMID 37334370, 2023). "In the current study, we demonstrated that db/db mice lacking Smad3 were protected against the development of type-2 diabetic phenotype, characterized by a normal body weight without severe obesity, normal levels of fasting blood glucose, no glucose intolerance nor insulin resistance." (PMID 33456576, 2021). "The expressions of fibrotic markers phosphorylated Smad3 and TGF-β were higher, whereas expression of anti-fibrotic phosphorylated Smad1/5 and BMP-2 were lower (all p<0.02); and LVEF was lower, whereas the LV remodeling was higher in obesity than in control and OR (all p<0.001)." (PMID 22784636, 2012). "In addition, we found that deletion of Smad3 in db/db mice protected against the development of hyperglycaemia, obesity, glucose intolerance and insulin resistance, while the normalised food intake was not significantly altered in Smad3 KO-db/db mice." (PMID 33456576, 2021). "Thus, the lack of CCN5 signaling may result in mild obesity, possibly through elevated TGF-β/Smad3 signaling activities." (PMID 34948212, 2021).
melanoma (48 papers, 2011 to 2025). A malignant, usually aggressive tumor composed of atypical, neoplastic melanocytes. "Analysis of the influence of Activin-A processing on SMAD3 signaling in a reporter cell line after Klk8 knockdown in furin-deficient B16-F1 melanoma cells revealed that this kallikrein converts proActivin-A to A70 independently of furin." (PMID 40064965, 2025). "Altogether, these results indicated that the SMAD3 signature is associated with resistance to both current melanoma therapies." (PMID 33724679, 2021). "The inhibitory effect of SMAD3i on melanoma cells seems to be associated with the total SMAD3 expression levels." (PMID 33724679, 2021). "A study analyzing 95 melanoma patients treated with ICIs found that genes affected by VARs associated with hypophysitis include SMAD3, PRDM1, and IL1RN, while genes affected by CNVs related to the occurrence of hypophysitis are TERT, SMAD3, JAK2, PRDM1, FAN1, CD274, and UNG." (PMID 37623461, 2023). "In melanoma, the TGFβ/Smad3 signaling pathway strongly suppresses tumorigenesis by blocking cell growth, immortalization, and cancer stem cell self-renewal activities, and by inducing cell death and autophagy." (PMID 38891107, 2024). "Using preclinical models of melanoma, we further showed that preventing Smad3/4 signaling, by means of CRISPR knockouts, promoted both tumorigenesis and lung metastasis in vivo." (PMID 38201651, 2024). "To further broaden the scope of our findings and further strengthen our results, we also used a parallel shRNA approach to knockdown Smad3 gene expression in BLM cells as well as in a third melanoma cell line (WM278)." (PMID 38201651, 2024). "SMAD3 plays a key role in melanoma resistance to treatment by promoting an EMT-like process, and their results suggest that the regulation of BRAF inhibitor resistance gene expression is multiparametric." (PMID 38084101, 2023). "Studies on PSMD14 were mainly associated with tumors, for example, targeting PSMD14 inhibited melanoma growth through SMAD3 stabilization." (PMID 35884735, 2022). "The stimulation of the TGFβ‐SMAD3 pathway by the recombinant TGFβ promoted the SMAD3 signature in these melanoma cell lines." (PMID 33724679, 2021). "We demonstrated that SMAD3i reduced the transcriptional activity of SMAD3 in response to TGFβ exposure in 4 melanoma cell lines." (PMID 33724679, 2021). "Firstly, we validated the inhibitory efficiency of SMAD3i in melanoma cells since it decreased the levels of phospho‐SMAD3 Ser423/425 induced by TGFβ in accordance with previous studies." (PMID 33724679, 2021). "Having shown that SMAD3 expression mediates BRAFi‐resistance and tumor growth, we explored the transcriptional program promoting its expression in BRAFi‐resistant melanoma cells." (PMID 33724679, 2021). "Next, we examined the SMAD3 signature in a large panel of melanoma cell lines representative of the distinct differentiation states (U ‐ NC ‐T ‐ M) (n = 53) and cutaneous melanoma (n = 118, TCGA cohort, tumors not exposed to targeted therapy)." (PMID 33724679, 2021). "The qRT-PCR was performed to evaluate the expression levels of matrix metallopeptidase 3 (MMP-3), SMAD2, SMAD3, caspase-8, caspase-9, and miR-214 in order to reveal the rCTII-induced signaling pathways in melanoma." (PMID 33167431, 2020). "For example, Gli1 and Gli2 are transcriptional targets of Transforming Growth-Factor-β/Smad3 in melanoma." (PMID 33228057, 2020). "Our results suggest that alteronol induces cyto-protective autophagy in melanoma cells through inhibition of Akt/mTOR pathway, thus attenuates apoptosis and promotes melanoma cell EMT through TGF-β/Smad3 pathway." (PMID 32265437, 2020). "Following treating melanoma cells with rCTII, there was a significant down-regulation in the expression level of SMAD2 and SMAD3 compared to untreated melanoma cells (both p < 0.01)." (PMID 33167431, 2020).